RPS6 (ribosomal protein S6)
Diseases named in the same sentence as RPS6 in open-access papers (continued):
Sharing a sentence is not in itself a finding about the gene and the disease.
schizophrenia (3 papers, 2020 to 2025). A major psychotic disorder characterized by abnormalities in the perception or expression of reality. "Finally, mTORC1-dependent signaling has been linked in post-mortem animal studies with schizophrenia, specifically the hypofunction of the ribosomal protein S6." (PMID 33922377, 2021). "One of the most recent findings that may underlie the mechanism of schizophrenia development is the hypofunction of ribosomal protein S6 in the prefrontal cortex of patients with schizophrenia, which is an effector of the mTOR pathway and plays an important role in regulating protein synthesis." (PMID 40566484, 2025). "To go through this hypothesis, we quantified the protein expression and phosphorylation of the mTOR downstream effector ribosomal protein S6 as well as other pathway interactors such as Akt and GSK3β, in postmortem PFC from subjects with schizophrenia and control subjects." (PMID 32265715, 2020).
Sepsis (3 papers, 2011 to 2023). Sepsis is defined as life-threatening organ dysfunction caused by a dysregulated host response to infection. "Although the phosphorylation level of Akt and 4E-BP1 remained unchanged in the gastrocnemius muscle after sepsis, both p70S6k and rpS6 phosphorylation were significantly increased 4 days after CLP in gastrocnemius muscle." (PMID 28883493, 2017). "This higher Akt-mTOR-S6k signaling was unexpected, since phosphorylations at relevant sites of Akt, mTOR, 4E-BP, S6k and S6k's downstream substrate ribosomal protein S6 are decreased in muscles of different animal models of sepsis and burn injury." (PMID 21483870, 2011).
tauopathy (3 papers, 2021 to 2025). Neurodegenerative disorders involving deposition of abnormal tau protein isoforms (tau proteins) in neurons and glial cells in the brain. "In particular, tau interacts with ribosomal protein S6 (rpS6 or S6), which is a crucial regulator of translation, and as a consequence, reduced protein synthesis has been observed under tauopathy conditions in AD." (PMID 40855644, 2025). "Increased RPS6 signalling has previously been observed in other models of tauopathy, with the phosphorylation of RPS6 being increased when hTau was co-expressed with the tyrosine kinase, Fyn." (PMID 34147135, 2021). "While hyperphosphorylated Tau drives the formation of neurofibrillary tangles as a major hallmark of AD, Tau was found to impair protein translation by disrupting ribosome biogenesis by interacting with rpS6 in the brains of AD patients and mice with tauopathy." (PMID 34393724, 2021).
Alzheimer disease (2 papers, 2016 to 2019). A progressive, neurodegenerative disease characterized by loss of function and death of nerve cells in several areas of the brain leading to loss of cognitive function such as memory and language. "Elevated rpS6 phosphorylation along with increased brain RBP4 levels were previously found in Alzheimer’s disease mice on a HFD." (PMID 27138913, 2016). "Consequently, protein synthesis under translational control of rpS6 was reduced under tauopathic conditions in Alzheimer’s disease brains." (PMID 30759285, 2019).
brain tumor (2 papers, 2015 to 2024). "In summary, we here present pitfalls and provide a recommendation for immunohistochemical assessment of mTORC1 signaling using phospho-specific antibodies against phospho-RPS6 (Ser235/236), phospho-RPS6 (Ser240/244), phospho-4EBP1 (Thr37/46) in routine FFPE brain tumor specimens." (PMID 25993328, 2015).
breast tumor (2 papers, 2023 to 2025). "Indeed, the prognostic value of RPS6 was assessed by Kaplan–Meier plotter analysis of GEx data from estrogen receptor positive/HER2 negative breast tumor samples of 686 patients." (PMID 36775056, 2023).
Cachexia (2 papers, 2019 to 2025). Severe weight loss, wasting of muscle, loss of appetite, and general debility related to a chronic disease. "At the onset of cachexia, rpS6 and eIF2α signalings were concomitantly activated in the liver, with increased expression of activating transcription factor 4 (ATF4) target genes involved in amino acid synthesis and transport, as well as autophagy." (PMID 40124481, 2025).
Cerebral ischemia (2 papers, 2015 to 2022). Restriction of arterial blood supply to the brain associated with insufficient oxygenation to support the metabolic requirements of the tissue. "Therefore, we believe that the downregulation of rpS6 signal transduction may be an important reason for the increased cell tolerance to cerebral ischemia observed during hibernation numbness and after ischemic preconditioning, by inhibiting protein synthesis and/or energy expenditure." (PMID 35027937, 2022).
cholangiocarcinoma (2 papers, 2021 to 2025). A carcinoma that arises from the intrahepatic biliary tree (intrahepatic cholangiocarcinoma) or from the junction, or adjacent to the junction, of the right and left hepatic ducts (hilar cholangiocarcinoma). "A recent study conducted in cholangiocarcinoma cells showed that overexpression of RPS6 is associated with tumour cell proliferation and silencing of RPS6 results in cell cycle arrest and reduced tumorigenicity." (PMID 40940922, 2025). "Supporting this view, a decrease in DNA replication was observed in cholangiocarcinoma cells upon silencing of RPS6." (PMID 40940922, 2025). "Besides, the phosphorylation of 70S6K (Thr389) and the phosphorylation of RPS6 (Ser235/236) were also drastically decreased in cholangiocarcinoma." (PMID 34462427, 2021).
chordoma (2 papers, 2009 to 2020). Chordomas are rare malignant tumors arising from embryonic remnants of the notochord in axial skeleton. "The remaining 17 p-mTOR-negative chordomas were positive for p-p70S6K, 9 of 15 (60%) of which were immunoreactive for total mTOR, but only one of these cases was positive for RPS6." (PMID 19401700, 2009). "It is not clear how loss of RPS6 contributes to the development of neoplasia although its allelic loss has also been reported in chondrosarcomas, a tumour with similarities to chordomas." (PMID 19401700, 2009). "Analysis of 50 chordomas showed that a high percentage of tumors were positive for p-AKT, piTSC2, p-mTOR, total mTOR, p-P70S6K, p-RPS6, p-4EBPI and eIF-4E45." (PMID 32737414, 2020). "Chordomas were positive for p-AKT (92%), p-TSC2 (96%), p-mTOR (27%), total mTOR (75%), p-p70S6K (62%), p-RPS6 (22%), p-4E-BP1 (96%) and eIF-4E (98%)." (PMID 19401700, 2009). "Thirty-eight of 49 (78%) chordomas were negative for p-RPS6 and 22 of 35 analysable cases (no data for 3 cases of the 38) showed no expression of the total protein RPS6." (PMID 19401700, 2009). "Approximately 50% of the p-mTOR-negative chordomas (16 of 33: 12 of which were immunoreactive for total mTOR) showed activation of neither p70S6K nor RPS6." (PMID 19401700, 2009). "In view of the importance of ribosomal synthesis in cell growth, the absence of RPS6 protein expression in 58% of chordomas is striking but appears to be a robust result because the IHC data are supported by the finding of RPS6 allelic loss in 21 of the 23 cases." (PMID 19401700, 2009).
Diabetes (2 papers, 2024 to 2025). "Regarding anabolic signaling pathways, the phosphorylation levels of key proteins, including AKT, mTOR, and rpS6, were differentially affected by diabetes and RSV treatment." (PMID 40004135, 2025).
insulinomas (2 papers, 2016 to 2021). "It appears, therefore, that rpS6 phosphorylation deficiency restrains the development of insulinoma by a mechanism that is distinct from that operated in S6K1 knockout mice." (PMID 26919188, 2016). "Strikingly, while rpS6 phosphorylation was nearly excluded from islets of 12-Mo old WT mice, it became readily detectable in insulinoma cells in aged-matched Akttg mice." (PMID 26919188, 2016). "Surprisingly, we found that Akt1 controls β-cell size in an rpS6 phosphorylation-independent fashion, yet the development of insulinomas in Akttg mice is abolished if their β-cells lack rpS6 phosphorylation." (PMID 26919188, 2016). "We show here that rpS6 knockin mutant β-cells are protected from the development of Akt-induced insulinoma, in a manner that resembles that observed in early human ribosomopathies (i.e. suppressed proliferation)." (PMID 26919188, 2016). "In order to examine whether augmented phosphorylation of rpS6 is a byproduct or, alternatively, a prerequisite for the tumorigenic process, we searched for insulinoma in rpS6P-/-;Akttg mice." (PMID 26919188, 2016). "Mechanistically, rpS6 phosphorylation deficiency failed to protect β-cells from Akttg induced aneuploidy, and therefore, does not block insulinomas development by interfering with their ploidy." (PMID 26919188, 2016). "Combined with the inhibitory effects of rpS6 mutants on insulinoma development, this finding indicates that aneuploidy is not sufficient for malignant transformation of β-cells, and that deficient phosphorylation of rpS6 does not prevent insulinomas development by interfering with ploidy." (PMID 26919188, 2016). "Conceivably, the expression of constitutively active Akt1 could induce insulinoma via activation of the mTORC1 pathway and thereby its downstream effectors, S6K1 and rpS6 phosphorylation in β-cell (and the present report)." (PMID 26919188, 2016).
ischemic stroke (2 papers, 2022 to 2025). A stroke disorder caused by obstruction of blood flow to the brain, due to thrombotic (local blood clot formation) or embolic (due to a blood clot or other material traveling from another site) event. "However, the dysfunction of RPS15A, RPS6, and RPS28 in females with ischemic stroke patients has never been reported." (PMID 35432523, 2022).
liver disease (2 papers, 2021 to 2023). "Our results show that both immature and adult hepatocytes depend on Rps6 for survival and that the developmental timing of deletion profoundly impacts the severity of liver disease." (PMID 36656901, 2023). "We found a negative correlation between the progression of liver disease and the phosphorylation of rpS6." (PMID 34385447, 2021).
metastatic disease (2 papers, 2016 to 2018). "We assessed the ratio of RON, phosphorylated mTORC1, and phosphorylated rpS6 to the epithelial marker EpCAM and did not see a direct correlation between high levels of total RON protein and levels of activated mTORC1 or rpS6 in primary or metastatic disease." (PMID 30456298, 2018).
neuroblastoma (2 papers, 2014 to 2021). Neuroblastoma (NB) is the most common solid, extracranial childhood tumor. "We show that in ALK-mutated, MYCN-amplified neuroblastoma cells, crizotinib alone does not affect mTORC1 activity as indicated by persistent RPS6 phosphorylation." (PMID 25228590, 2014).
ovarian tumor (2 papers, 2020). "In this study, we also showed that the inhibition of ribosomal protein S6 is a good indicator of a protein synthesis suppression, which could be a mechanism that impairs ovarian tumor growth." (PMID 33488949, 2020). "RPS6 was mainly distributed in the nucleus of ovarian tumor cells." (PMID 32862831, 2020).
pancreatic ductal adenocarcinoma (2 papers, 2016 to 2021). An infiltrating adenocarcinoma that arises from the epithelial cells of the pancreas. "It has previously been shown that rpS6 phosphorylation is critical for Kras-induced PanIN lesion formation in the exocrine pancreas and for full-blown pancreatic ductal adenocarcinoma induced by a carcinogen." (PMID 26919188, 2016).
squamous cell carcinoma (2 papers, 2015 to 2024). A carcinoma arising from squamous epithelial cells. "Similar prognostic significance of p-rpS6 was also found in I and II stage esophagus squamous cell carcinoma subjects, substantiating the important early predictive values of p-rpS6." (PMID 26490682, 2015).
acute leukemia (1 paper, 2015). A clonal (malignant) hematopoietic disorder with an acute onset, affecting the bone marrow and the peripheral blood. "The inhibition of PI3K/AKT/mTOR signaling suppressed the ribosomal protein S6 (RPS6) in acute leukemia subjects." (PMID 26275051, 2015).
alcohol addiction (1 paper, 2023). "However, four genes, SERPINA3, SLC14A1, RPS6 and RPS3A, were obtained among the alcohol addiction-related differential genes." (PMID 37065902, 2023).
allergic reaction (1 paper, 2025). "The mechanisms leading to higher phosphorylation of RPS6 in adults with severe allergic reactions as well as its biological implications remain to be elucidated." (PMID 40932794, 2025).
anemia (1 paper, 2021). A reduction in the number of red blood cells, the amount of hemoglobin, and/or the volume of packed red blood cells. "Although mutations of the RPS6 gene have not been reported in this anemia, mice lacking one Rps6 allele postnatally display features of the 5q-syndrome, such as macrocytic anemia, erythroid hypoplasia, and megakaryocytic dysplasia with thrombocytosis." (PMID 35008473, 2021).
Anorexia (1 paper, 2020). Lack of desire to eat (loss of appetite). "Our results showed that phosphorylation of the ribosomal protein S6 level was significantly higher in the mandarin fish of Group B, suggesting that the anorexia was related to the activation of mTOR pathway." (PMID 32636801, 2020).
asthma (1 paper, 2025). "Airways from individuals with severe asthma showed increased MTOR signaling by RPS6 phosphorylation, which was reproduced using an IL-13–activated model of primary human airway epithelial cells (hAEC)." (PMID 40446022, 2025). "First, MTOR phosphorylation of substrate RPS6 was increased along the epithelium from individuals with severe asthma, particularly in regions rich in GC." (PMID 40446022, 2025). "In contrast, a recent study reports a different finding with decreased phospho-RPS6 in asthma airway sections, mouse lungs, and undifferentiated hAEC." (PMID 40446022, 2025). "We found a significant increase in phospho-RPS6 staining in asthma epithelial sections compared with controls." (PMID 40446022, 2025). "We examined the airway sections from nonasthma controls and individuals with severe asthma for MTOR activation using phosphorylated serine 240/244 (phospho-RPS6), which regulates key MTOR-dependent signaling pathways in cell proliferation, cell size, and protein synthesis." (PMID 40446022, 2025).
Atrophy (1 paper, 2010). Any weakening or degeneration, especially through lack of use. "Here we present evidence that in MAFbx-induced atrophy thedegradation of eIF3f suppresses S6K1 activation by mTOR, whereas an eIF3f mutantinsensitive to MAFbx polyubiquitination maintained persistent phosphorylation ofS6K1 and rpS6." (PMID 20126553, 2010).
autism (1 paper, 2019). Persistent deficits in social interaction and communication and interaction as well as a markedly restricted repertoire of activity and interest as well as repetitive patterns of behavior. "Finally, as we identified four proteins (p-eIF4E, rpS6, TSC1 and p-MNK1) that demonstrated an association with the clinical severity, we wanted to investigate if, together, those proteins could constitute a molecular signature for autism severity." (PMID 30705255, 2019).
autism spectrum disorder (1 paper, 2019). A spectrum of developmental disorders that includes autism, and Asperger syndrome. "Specifically, rpS6, p-eIF4E, TSC1 and p-MNK1 expression discriminated patients according to their clinical diagnosis, suggesting that components of protein synthesis signalling pathways might constitute a molecular signature of clinical severity in autism spectrum disorder." (PMID 30705255, 2019).
bladder tumor (1 paper, 2023). "Further Western blotting analysis of bladder tumor tissues revealed that dietary kawain resulted in a reduced protein expression of 4E-BP1 and phosphorylation of rpS6." (PMID 36838656, 2023).
cardiac hypertrophy (1 paper, 2016). "However, deletion of S6K1 and S6K2 and thereby elimination of rpS6 phosphorylation had no impact on the development of pathological, physiological, or genetically induced cardiac hypertrophy." (PMID 26919188, 2016).
cervical squamous cell carcinoma (1 paper, 2022). A squamous cell carcinoma arising from the cervical epithelium. "Upregulation of RPS6 is involved in cancer cell proliferation, distant metastasis, and poor prognosis in breast and cervical squamous cell carcinoma." (PMID 36293493, 2022).
cholestasis (1 paper, 2023). Impairment of the bile flow caused by obstruction within the liver, or outside the liver in the bile duct system.
Cognitive impairment (1 paper, 2024). Abnormal cognition is characterized by deficits in thinking, reasoning, or remembering. "Studies have shown that mycophenolate mofetil reduces neuron death and improves the cognitive impairment caused by epileptic seizure, which may be related to the decreased expression of Rps6 in the hippocampus." (PMID 38421132, 2024).
cyst (1 paper, 2021). A sac-like closed membranous structure that may be empty or contain fluid or amorphous material. "In order to validate the drug target, we utilized specific antibodies for mammalian phosphorylation RPS6 to perform IHC on cyst epithelial cells and found distinct expression of pRPS6 in cysts from different sources." (PMID 34815804, 2021).
cystadenoma (1 paper, 2020). A benign or borderline cystic epithelial neoplasm arising from the glandular epithelium. "Kidneys from Tsc1∆/∆ mice also exhibited multiple cystadenomas and increased immunostaining of phosphorylated ribosomal protein S6 (pS6) compared to Tsc1+/+ mice, consistent with constitutive mTOR activation following Tsc1 deletion." (PMID 32927859, 2020).
cystic kidneys (1 paper, 2016). "Although a decrease in PCNA, ribosomal protein S6, and β‐catenin levels occurred in cystic kidneys after 26 days, levels of these markers remained elevated compared to age‐matched control kidneys through 180 days of age." (PMID 27356569, 2016). "PCNA, β‐catenin, and Smad2 were elevated in cystic kidneys compared to age‐matched controls by 18 days of age, and the phosphorylated forms of both Erk and ribosomal protein S6 were elevated compared to wild‐type controls by 26 days of age." (PMID 27356569, 2016). "A decrease in ribosomal protein S6 phosphorylation did not occur in cystic kidneys, even at 180 days of age, whereas wild‐type kidneys down‐regulate S6 phosphorylation by 26 days of age." (PMID 27356569, 2016).
developmental delay (1 paper, 2011). "As the original RpS6air8 line was no longer available to confirm the previous findings, we demonstrated suppression of cycEJP using an alternate RpS6 mutation, RpS6WG1288, which also exhibits the classic Minute phenotype of slender bristles (not shown) and a developmental delay (red data points)." (PMID 22194697, 2011).
emphysema (1 paper, 2022). "Quantification of the protein levels of RPS6 and phosphorylated RPS6 (p-RPS6) in lung lysates derived from normal and emphysema patients (n = 21 for each group)." (PMID 35384838, 2022). "However, we observed heterogeneous expression of p-RPS6 in emphysema lungs." (PMID 35384838, 2022). "We did not detect a difference in the protein levels of either RPS6 or p-RPS6 in lysates from emphysema and normal lungs." (PMID 35384838, 2022).